AR (androgen receptor)
Diseases named in the same sentence as AR in open-access papers (continued):
Sharing a sentence is not in itself a finding about the gene and the disease.
prostate carcinoma (continued). "Prostate cancer treatments, such as androgen receptor axis-targeted therapies (ARATs, i.e., abiraterone acetate, apalutamide, darolutamide, and enzalutamide), may interact with common antithrombotic medications like warfarin, clopidogrel, and the direct oral anticoagulants." (PMID 39409956, 2024). "Therefore, the repressive effects of PHB may inhibit AR, E2F and WNT expression and its loss may increase metastatic potential in human prostate cancer." (PMID 37373067, 2023). "Our findings support the hypothesis that the AR is a tumor suppressor in prostate cancer." (PMID 37142586, 2023). "The ability of semaphorin 3C to promote intratumoral androgen synthesis may be a key mechanism contributing to the reactivation of the androgen receptor pathway in castration-resistant prostate cancer, conferring continued growth under androgen deprivation therapy." (PMID 37800655, 2023). "In fact, AR-Vs are significantly expressed in castration resistant prostate cancer (CRPC) compared to hormone-naive prostate cancer, with androgen receptor variant 7 (AR-V7) expressed in 75% of CRPC cases following ADT and less than 1% of primary prostate cancer cases." (PMID 37191417, 2023). "Namely, the AR, in interaction with ITGB1 and membrane type-matrix metalloproteinase 1 (MT-MMP-1 or MMP14), activates a protease cascade triggering ECM remodeling, which facilitates the cancer-associated fibroblast invasion through the ECM and a subsequent interaction with prostate cancer cells." (PMID 38255186, 2023). "Moreover, AR antagonists could increase the sensitivity of AR-positive prostate cancer cells to ferroptosis by downregulating MBOAT2 directly." (PMID 37735316, 2023). "Having identified SRC kinase as a key tyrosine kinase enriched in CRPC patient tumors from our previous work, we evaluated whether inhibition of SRC kinase synergizes with enzalutamide or chemotherapy in several prostate cancer cell lines expressing variable AR isoforms." (PMID 37456235, 2023). "Therefore, we hypothesized that a new type of AR inhibitor could serve as a unique therapeutic agent for prostate cancer." (PMID 37744273, 2023). "When the hormonal ligands testosterone and 5‐dihydrotestosterone bind to AR, it dissociates from accessory proteins and transfers to the nucleus, triggering the expression of genes involved in cell proliferation and evasion of apoptosis, thereby boosting prostate cancer development." (PMID 36018061, 2023). "In this review, we discussed the transcriptional/epigenetic regulatory functions of AR, with emphasis on the clinical applications of AR ligands, AR protein co-regulators, and AR RNA coregulator (enhancer RNA), especially in chromatin reorganization, in patients with prostate cancer." (PMID 37025180, 2023). "Therefore, AR inhibition is a potential mechanism for DTX within prostate cancer treatment." (PMID 37326412, 2023). "However, the effectiveness of ADT is limited, and prostate cancer cells can eventually develop resistance to this therapy by finding alternative ways to activate the androgen receptor signaling pathway, leading to development of castration-resistant prostate cancer (CRPC)." (PMID 37104249, 2023). "Because resistance to AR-targeted therapies is driven, in part, by cellular plasticity, we posit that DNMTs could serve as potentially actionable targets to limit therapy-driven cellular plasticity in prostate cancer." (PMID 37900138, 2023). "Furthermore, AR overexpression increases FEN1 protein production in prostate cancer cells." (PMID 37326412, 2023). "Thus, targeting the AR/SP1 translational complex showing therapeutic potential in prostate cancer." (PMID 36744249, 2023). "Therefore, it may be critical to develop therapeutic strategies for castration-resistant prostate cancer (CRPC) that extend beyond targeting AR pathways." (PMID 37104245, 2023).
prostate carcinoma (continued). "Subsequently, DHT and T bind to and initiate androgen receptor (AR) nuclear translocation, which results in AR target gene transcription that modulates cell cycle, apoptosis, cell differentiation, and other processes necessary for the development and progression of prostate cancer." (PMID 36837903, 2023). "Thus we explored whether AR knockdown promoted toxicity effects of DTX on prostate cancer cell growth." (PMID 37326412, 2023). "Recent advances in precision medicine, androgen receptor targeting, immunotherapy, radiation therapy, and active surveillance may (individually or in combination) improve therapy decisions for locally advanced prostate cancer." (PMID 37373928, 2023). "Consequently, targeting AR alone might not provide therapeutic efficacy; hence, co-targeting the PCSCs with AR could improve the therapeutic efficacy against the prostate cancer." (PMID 36969009, 2023). "This is because Hsp90 is commonly overexpressed in prostate cancer compared to normal prostate cells; prostate cancer cells are selectively sensitive to Hsp90-directed agents; and Hsp90 clients include the androgen receptor, a major driver of prostate tumorigenesis." (PMID 36743211, 2023). "From the groundbreaking studies of Huggins and Hodges to the development of novel, second-generation androgen receptor inhibitors, and anti-androgens, much of the existing treatment options for prostate cancer are currently focused on targeting the androgen receptor (AR) signaling axis." (PMID 37228586, 2023). "Our findings further imply that the cavitation-induced sonoporation may be connected to the additive effects of FUS on HT, with potential mechanisms including the induction of DSBs, cell cycle arrest, and blocking of the AR signaling pathway in prostate cancer cells." (PMID 37152995, 2023). "The metastatic behaviour of prostate cancer cell lines influenced cell attachment and proliferation, with the more prolific androgen-receptor-negative PC-3 cells demonstrating higher attachment rates and proliferation compared to androgen-receptor-positive cell lines." (PMID 36678871, 2023). "Briefly, they involve AR-centric (for example, the expression of constitutively active AR variants) and AR-independent mechanisms, which might include the activation of FGFR or modulation of the WNT pathway to drive AR-independent growth of prostate cancer." (PMID 38255186, 2023). "However, the prospect of overt AR stimulation, even transiently, in the treatment of localized prostate cancer poses difficulties in clinical implementation given the dependence on and stimulation of prostate cancer growth from AR signaling." (PMID 38104131, 2023). "Therefore, compared to abiraterone, enzalutamide may act more selectively and comprehensively on the AR signaling pathway in prostate cancer cells." (PMID 37077831, 2023). "Thus, combined inhibition of Prx1 and AR or disruption of Prx1–TDP52 interaction might represent a promising treatment strategy for prostate cancer treatment." (PMID 37237480, 2023). "Therefore, we speculate that AR enhances the DDR of prostate cancer cells by regulating FEN1 expression, which in turn promotes tumour growth and resistance to ADT or chemotherapy." (PMID 37326412, 2023). "Because Arc is a potent inhibitor of AR signaling in LAPC-4 prostate cancer cells, the combined effects of Arc and quercetin on proliferation, apoptosis, cell migration, and underlying mechanisms in both androgen-dependent prostate cancer cell lines (LNCaP and LAPC-4) have been reviewed." (PMID 36926328, 2023). "Thus, targeting AR signaling is a pillar of advanced prostate cancer treatment strategies." (PMID 37445854, 2023). "Moreover, several preclinical studies have indicated that androgen receptor (AR) signaling antagonists may enhance the sensitivity of prostate cancer cells to PARPi." (PMID 37812088, 2023).
prostate carcinoma (continued). "RNA sequencing reveals that KLK3 (PSA) and other transcriptional target genes of AR are significantly downregulated upon VNPP433-3β treatment besides inhibiting transcription of several genes in pathways critical for prostate cancer progression in prostate cancer cells." (PMID 36831540, 2023). "Therefore, the AR inhibitors approved for prostate cancer treatment could constitute a therapeutic tool for breast cancer, and become a new direction for endocrine therapy of breast cancer." (PMID 38114991, 2023). "LNCaP, an established human prostate carcinoma cell line, has been used in the study of PCa progression, during different stages and in response to several therapies, specifically involving AR signaling, since LNCaP cells present the unique ability to express AR." (PMID 38068717, 2023). "The inhibition of AR activity may delay prostate cancer progression." (PMID 37175938, 2023). "Thus, ca27 induces ROS production and downregulates AR by an oxidative stress mechanism, suggesting that ca27 could be a good anti-androgenic compound to treat patients with advanced prostate cancer." (PMID 37296999, 2023). "The androgen receptor plays a key role in prostate cancer development and progression; therefore, the inhibition of its expression/function could significantly improve the therapeutic approach against prostate cancer." (PMID 37296999, 2023). "This study suggests that SMAD3 could be targeted to inhibit AR in prostate cancer." (PMID 36727462, 2023). "In prostate cancer, reduced PSAP staining was strongly linked to an advanced pT stage, a high classical and quantitative Gleason score, lymph node metastasis, high pre-operative PSA levels, early PSA recurrence (p < 0.0001 each), high androgen receptor expression, and TMPRSS2:ERG fusions." (PMID 37892063, 2023). "Moreover, the activation of the DDR mediators caused by AR and NKX3.1 activation in androgen-responsive and castration-resistant prostate cancer cells indicated that the androgen receptor function is essential both in controlling oxidative stress and in activating the ROS-induced DDR." (PMID 38155939, 2023). "Aside from AR signaling, the tumor may eventually adapt to the low levels of androgen resulting from androgen lowering therapeutic strategies, activating alternative mechanisms for activating AR or by bypassing AR, developing into the castration-resistant form of prostate cancer." (PMID 37894395, 2023). "Recently, hormonal therapy using abiraterone acetate, a second‐generation androgen receptor axis‐targeted agent, was reported to improve overall survival and progression‐free survival in men with LATITUDE‐high‐risk metastatic castration‐sensitive prostate cancer." (PMID 34863085, 2022). "Therefore, clinical therapies use anti-androgens (Flutamide, Bicalutamide, Enzalutamide, Apalutamide, and Darolutamide) to competitively suppress androgen-induced AR activation or CYP17A1 inhibitor (Abiraterone) to reduce androgen production in prostate cancer tissues." (PMID 35372068, 2022). "Therefore, it has been suggested that GR inhibition may be useful together with AR antagonists for treating prostate cancer." (PMID 35761157, 2022).
prostate carcinoma (continued). "Finally, we tested the hypothesis that high translation rates were important to maintain AR-low prostate cancer heterogeneity using the Ptenfl/fl;4ebp1M mouse model." (PMID 36511483, 2022). "Aberrant expression of AR bearing short polyglutamine (polyQ) tracts (e.g., hAR12Q) and stabilized β-catenin has also been shown to induce the early onset of tumors and accelerate invasive prostate cancer progression relative to those carrying long polyQ tracts (e.g., hAR48Q)." (PMID 35204808, 2022). "In addition, the overexpression of JAG1 and JICD in PPC-1 cells (AR-negative PC-3-derived prostate cancer cells) markedly enhanced the androgen-dependent and androgen-independent transactivation of exogenous AR-FL, AR-NTD-DBD, and AR-V7 in a dose-dependent manner." (PMID 36428807, 2022). "Interestingly, we found that TRIB2 downregulates the luminal markers androgen receptor and cytokeratin 8 in prostate cancer cells but upregulates the neuronal transcription factor BRN2 (Brain-2) and the stemness factor SOX2 (SRY-box 2) to induce neuroendocrine characteristics." (PMID 34973338, 2022). "However, cellular consequences of AR‐repressive function in prostate cancer cells remain elusive." (PMID 34919781, 2022). "Treatment of prostate cancer with AR inhibition may lead to selection for cancer cells with elevated ONECUT2 expression, thereby contributing to resistance to AR-targeted therapy and development of NE features that lead to more aggressive phenotypes with worse clinical outcomes." (PMID 35582526, 2022). "In addition, data mining of single-cell transcriptome further confirmed the existence of ARHIGH/NEHIGH prostate cancer cells in castration-resistant samples and suggested that AR still exerts its androgen response and anti-apoptotic effect in these double-high cells." (PMID 36033483, 2022). "Therefore, dual HDAC6/AR inhibitors are likely to produce synergistic effects that may conveniently be utilized as a new approach for the treatment of prostate cancer." (PMID 36034650, 2022). "Furthermore, there are four related literatures on the PubMed website reporting the relationship between CREB5 and tumor resistance, of which only one paper preliminarily clarified the molecular mechanism of CREB5 promoting prostate cancer resistance to androgen receptor antagonists." (PMID 35773668, 2022). "Additionally, as our knowledge of AR in the cells of the microenvironment increases, targeting specific coregulators may also provide novel means of treating advanced prostate cancer." (PMID 37435460, 2022). "In addition, TR3 expression was detected in all tested AR-positive prostate cancer cell lines in spite of a very low basal level in LNCaP cell line, but not in AR-negative prostate cancer cell lines and was induced by 5α-dihydrotestosterone (DHT), indicating TR3 as an androgen-responsive gene." (PMID 35454821, 2022). "Moreover, vinclozolinM2-2204 exhibited DC50 of ~200 nM for AR in LNCaP prostate cancer cells." (PMID 35173167, 2022). "In our study we show a counter-regulatory link between AR and NF-κB both in human cells and in mouse models of prostate cancer, implying that inhibition of AR signaling results in induction of NF-κB-dependent inflammatory pathways, which may even foster the survival of metastasizing cells." (PMID 36551650, 2022). "One possible explanation may be that prostate cancer patients with diabetes may represent a unique subpopulation in which the PSMA expression correlates with both the androgen receptor expression as well as insulin and the insulin growth factor receptor expression." (PMID 35330410, 2022). "Thus, DNMT inhibitors may be a promising class of drugs to restore AR expression in subsets of AR-null prostate cancer." (PMID 35909568, 2022). "Additionally, IR treatment caused a marked induction of the androgen target genes TMPRSS2 and FKBP5 in prostate cancer cells, suggesting that DNA damage may directly induce AR activity." (PMID 35954292, 2022).
prostate carcinoma (continued). "Ginsenoside Rb1 inhibited vascular calcification as a selective androgen receptor modulator as evidenced by exhibiting inhibitory effects on vascular smooth muscle cells (VSMCs) calcification through androgen receptor-mediated Gas6 transactivation and antagonistic effects in prostate cancer cells." (PMID 36501028, 2022). "The Fucci2BL live cell cycle tracking system in these unique prostate cancer bone metastasis organoids revealed not only that enzalutamide induced dormancy but also that the length of the cell cycle was very long even in the presence of androgen receptor function." (PMID 35328625, 2022). "However, uroA remarkably promoted Akt phosphorylation, which might be due to the significant suppression of AR activity in uroA-treated prostate cancer cells." (PMID 35280689, 2022). "Thus, AR activity can be downregulated or upregulated by HDACs and KDMs, and the development and progression of prostate cancer is accompanied by extensive abnormalities in the levels of these enzymes and in histone modification marks, which has been referred to as an ‘epigenetic catastrophe’." (PMID 34986150, 2022). "Given that androgen receptor dampens tissue factor, a pivotal mediator of coagulation and VTEs, expression via nuclear factor-kappa B (NF-κB) and early growth response protein 1, increased tissue factor expression is expected in androgen-deprived prostate cancer patients." (PMID 35369325, 2022). "In addition, this pathway is regulated by the androgen receptor in prostate cancer cells, suggesting that the hyperandrogenism characteristic of PCOS could modulate the gene expression and phenotype of ABD-derived ASCs." (PMID 35269469, 2022). "Therefore, ABCC5 enhances the expression of phosphorylated P65, which in turn activates transcription by binding to the downstream AR promoter to enhance AR protein expression and pre-mRNA splicing, ultimately promoting enzalutamide resistance in prostate cancer." (PMID 35504877, 2022). "Moreover, LSD1 may also function as an upstream activator of androgen receptor signaling in prostate cancer." (PMID 35707047, 2022). "According to these authors, PC cells may exhibit high levels of expression of the small glutamine-rich tetratricopeptide repeat-containing protein alpha (SGTA), a molecule involved in the inhibition of AR signaling in androgen-independent human and canine prostate cancer cells." (PMID 35681707, 2022). "Therefore, our results may suggest a hypothesis that men with detectable skatole concentration in the serum are less likely to develop/have AR-dependent prostate cancer." (PMID 36613955, 2022). "We hypothesized that translation inhibition in AR-low prostate cancer might be lethal or confer a competitive disadvantage to AR low epithelial cells, and that the bulk of the remaining epithelia did not express the 4ebp1M and were simply castrate cells that did not express the transgene." (PMID 36511483, 2022). "The NTD has attracted much attention not only because of its known participation in transcriptional activity but also, and in particular, because diverse C-terminally truncated splice variants of AR lacking the LBD have been identified in prostate cancer cell lines and in clinical specimens." (PMID 34986150, 2022). "However, whether overexpressed AR alone with the stimulation of castrate levels of androgens can be sufficient to induce the reprogramming of AR signaling for the adaptation of prostate cancer (PCa) cells remains unclear." (PMID 36408179, 2022). "Likewise, Arv7, a constitutively active androgen receptor splice variant lacking the ligand-binding domain, is present at low frequencies in de novo prostate cancer, but frequency increases upon treatment with ARSIs." (PMID 35269713, 2022).